EGFR (epidermal growth factor receptor)
Diseases named in the same sentence as EGFR in open-access papers (continued):
Sharing a sentence is not in itself a finding about the gene and the disease.
tumor (continued). "CAFs isolated from tumor tissues were capable of producing tryptophan metabolite kynurenine (Kyn), which significantly increased the proliferation and EGFR TKIs resistance of NSCLC cells." (PMID 35831824, 2022). "EGF facilitated the adhesion of EGFR+ tumor cells with TAMs through ICAM-1–αMβ2 integrin interaction." (PMID 35682890, 2022). "Nimotuzumab is a humanised IgG1 monoclonal antibody that acts on the extracellular structural domain of EGFR and exerts its antitumour effects mainly by inhibiting tumour cell proliferation, anti-angiogenesis, and promoting apoptosis." (PMID 36263226, 2022). "The ORR among the patients with EGFR+ NSCLC with ≥ 25% of tumor cells expressing PD-L1 remained encouraging (12.2%) relative to that (4%) among patients with < 25% PD-L1 expression." (PMID 35444951, 2022). "Lrig1 has prognostic value in several cancers, including GBM, through its role as a tumour suppressor regulating EGFR activity." (PMID 36420140, 2022). "The EGFR was highly and differentially expressed in tumor samples between tumor-paracancer (p = 0.0301) and paired tumor-normal (p = 0.0451) samples." (PMID 36291859, 2022). "Blocking EGFR affects intracellular signaling, which is vital for tumor cell proliferation and survival." (PMID 36654821, 2022). "We suspect that patients with the p63high tumor subtype would benefit from a combination of EGFR and PI3K inhibitor treatment and radiotherapy." (PMID 35712470, 2022). "The tumor location also has therapeutic implications, mostly related to anti-epidermal growth factor receptor antibodies." (PMID 36505147, 2022). "The EGFR-TKI afatinib combined with radiotherapy significantly increases the anti-tumor effect of radiation in PC-9-GR cells harboring acquired T790M." (PMID 36556319, 2022). "To address EGFR dependency, we then challenged tumour cells with cetuximab, an EGFR neutralising antibody." (PMID 36380366, 2022). "Promising novel therapeutic approaches exploit the frequent overexpression of EGFR in a broad range of different cancers and the tumor immune microenvironment." (PMID 36185288, 2022). "With advances in sequencing technology, scientists have also identified new mutation sites, such as L747S, D761Y, and T854A, which also reduce the binding interactions between the drug and EGFR-TKI to induce tumor resistance." (PMID 35684449, 2022). "TPX2 expression was significantly increased in tumor tissue samples obtained from patients with advanced EGFR-mutant NSCLC after erlotinib treatment failure compared with results from pre-treatment samples." (PMID 35463360, 2022). "EGFR is the most well-known growth factor receptor that interacts with G protein-coupled receptors (GPCRs) and is involved in the regulation of tumor development, invasion, and progression in a variety of malignancies." (PMID 35409206, 2022). "This work created an experimental model of a heterogeneous tumor to find the best combination therapy regimen and proposes a basic notion of EGFR-TKI combination therapy to enhance the prognosis of NSCLC patients." (PMID 35304574, 2022). "This suggests that dysregulated metabolic pathways and miRNAs moderate tumor cells’ growth and adaptation to EGFR TKI in EGFR-driven cancer." (PMID 35840668, 2022). "Increasing levels of EGFR T790M or C-MET expression in plasma ctDNA after short-term EGFR-TKI treatment was closely related to EGFR T790M or C-MET amplification in the post-treatment tumor tissue." (PMID 35326664, 2022). "Despite these extensive attempts to improve survival outcomes for GBM patients with EGFR-expressing tumours, there is little clinical evidence supporting the benefit of EGFR-targeted therapies in GBM treatment." (PMID 36497413, 2022). "Third, co-expression of RON and epidermal growth factor receptor (EGFR) or MET were significantly associated with increased the risk of local recurrence, tumor invasion, and decreased patient survival." (PMID 36103228, 2022).
tumor (continued). "In this regard, we recently used the anti-EGFR CL4 aptamer to decorate cisplatin-loaded PNPs and proved the tumor-targeting, safety profile, and anti-tumor activity of the resulting nanovectors in mice bearing EGFR-positive TNBC." (PMID 36297659, 2022). "TK receptors, including epidermal growth factor receptor (EGFR), are overexpressed in several tumours." (PMID 36615397, 2022). "Koopmans and coworkers demonstrated that tumor-specificity can be increased by EGFR directed PD-L1 blockade, resulting in a potentially favorable safety profile of the described bsAb." (PMID 35479092, 2022). "Tumor cells with high SNHG scores were more sensitive to drugs targeting the EGFR and ERK-MAPK signaling pathways." (PMID 36159816, 2022). "This indicates that we can detect the majority of tumor cells in a sample with anti-EpCAM/anti-EGFR antibodies." (PMID 36613466, 2022). "Tumor mutation burden (TMB) was investigated by utilizing our panel and showed that EGFR L858R had the lowest TMB compared with other EGFR mutant subtypes." (PMID 36505399, 2022). "GSEA analysis designates that the transcriptomic aberrations in the fusion gene group exhibited more specific patterns in tumor-related pathways than the EGFR group." (PMID 35428753, 2022). "HNK activates MIG6 expression, leading to EGFR inhibition, and exerts anti-tumor effects and anti-fibrotic ones." (PMID 35453652, 2022). "Targeted therapies such as vascular endothelial growth factor (VEGF) inhibitors and epidermal growth factor receptor (EGFR) inhibitors are examined to effectively hinder angiogenesis and thus impede tumor growth." (PMID 35747126, 2022). "EGF can induce STAT3 activation and block the interaction between STAT3 and EGFR, which can inhibit tumor growth." (PMID 35547655, 2022). "Both EGFR and MET are widely expressed on tumor cells, and these RTKs are implicated in diverse tumor progression signaling processes." (PMID 36158893, 2022). "While E07 and H02 aptamers did not label non-tumoral tissues, they were efficient in detecting cells expressing EGFR and integrin α5β1 within the tumor." (PMID 36297416, 2022). "Taken together, these data demonstrated that EGFR overexpression completely reversed CB1 activation-induced tumor suppression." (PMID 35641479, 2022). "The PGRMC1 dimer binds to EGFR and cytochrome P450 and thereby enhances tumor cell proliferation and chemotherapy resistance." (PMID 36008941, 2022). "Binders that target mesothelin, epidermal growth factor receptor, prostate specific membrane antigen or other tumor antigens have been developed and are in clinical trials to treat diverse malignancies." (PMID 35185932, 2022). "Chloroquine (CQ) was used with AP/ES (anti-EGFR Aptamers- modified polyamidoamine) to restore tumor vasculature to provide optimal drug/gene delivery and overcome treatment resistance in NSCLC cells." (PMID 36085575, 2022). "Improved tumor immunity mediated by increased concentrations of sPD-1 seems to play a significant role in prolonged PFS and OS in specific patients with advanced EGFR-mutated NSCLC." (PMID 35300340, 2022). "For chromosome 18q11.2‐q12 no‐loss patients with RAS (KRAS and NRAS)/BRAF wildtype tumors and left‐sided location of the primary tumor, anti‐EGFR in the first‐line is a viable alternative, now recommended solely beyond the first‐line." (PMID 35489024, 2022). "Abnormal IGF-IR activation is observed in several resistant tumor cells targeted by anti-EGFR therapies." (PMID 35248049, 2022). "While a phase I clinical trial with advanced EGFR-driven NSCLC patients indicated durable tumour response rates upon combining ICB with erlotinib, the benefit of using this combination therapy approach is still not conclusively proven." (PMID 36010935, 2022). "In preclinical NSCLC models, such as patient-derived tumor xenograft models and cell lines, response rates to EGFR TKI therapy were improved by the addition of JAK or STAT3 inhibitors." (PMID 36010693, 2022).
tumor (continued). "Cetuximab specifically binds epidermal growth factor receptor (EGFR) and blocks the EGFR signaling pathway, thereby exerting anti-tumor activity." (PMID 35740594, 2022). "The results showed that IOMNPs binding to EGFR can specifically recognise tumor cells with high expression of EGFR." (PMID 36359744, 2022). "In the tumor microenvironment, the EGF receptor is often constantly stimulated, either by the sustained production of EGFR ligands or by a mutation in EGFR itself that keeps the receptor in a state of constant activation." (PMID 36499115, 2022). "It was reported that disease progression after EGFR TKI treatment leads to suppression of tumor-infiltrating CD8+ T cells and induction of regulatory T cells, resulting in a noninflamed TME and insensitivity to ICI monotherapy." (PMID 36082280, 2022). "The patient firstly received tumor excision surgery and then a TKI-sensitive mutation, EGFR L861Q, was detected from tissue sample by a 500-gene NGS panel." (PMID 35308511, 2022). "We previously produced a humanized recombinant immunotoxin, hDT806, targeting tumor-specific overexpressed EGFR and/or the EGFRvIII mutant." (PMID 35453686, 2022). "Epidermal growth factor receptor (EGFR) is closely related to cell differentiation, proliferation, and tumor metastasis and is involved in the proliferation, invasion, metastasis, and angiogenesis of many types of tumors." (PMID 35684522, 2022). "Mutations in oncogenic factors including EGFR, ALK, BRAF, or MET, which can change the immunological tumor micro-environment, can enhance tolerance to PD1/PD-L1." (PMID 36499382, 2022). "In approximately 50% of bladder tumors, EGFR is strongly expressed, predicting muscle invasion and poor tumor differentiation." (PMID 36230734, 2022). "This pathway was shown to contribute to tumor resistance to MET TKI; stromal HGF and tumor MCT4 were also upregulated in epidermal growth-factor receptor TKI-resistant tumors of NSCLC patients." (PMID 35565690, 2022). "Erlotinib, previously OSI-774, is an oral EGFR-specific ATP competitive TKI that has been shown to be potentially effective with EGFR-positive tumours." (PMID 36140214, 2022). "When EGFR siRNA is encapsulated in these NPs, it shows excellent tumor penetration, cell uptake level, EGFR silencing efficiency and tumor growth inhibition efficacy in U-87 MG GBM tumor spheroids in vitro and in xenograft tumor-bearing mice in vivo." (PMID 35874843, 2022). "The inhibition of EGFR was performed using cetuximab in tumor-bearing mice and was characterized by ETTE probe at day 0 and day 14, respectively." (PMID 35105871, 2022). "The E5 gene encodes for an oncogenic protein that contributes to the productive state of the viral cycle and tumor progression, with an important role in the epidermal growth factor receptor (EGFR) activation and immune evasion." (PMID 36552201, 2022). "In HPV-negative HNSCC, EGFR overexpression is known to promote tumour cell proliferation, disease progression and correlates with poor prognosis." (PMID 36333293, 2022). "EGFR is involved in tumour cell proliferation, angiogenesis, tumour invasion, metastasis, and inhibition of apoptosis." (PMID 35589670, 2022). "Our findings indicate that RBM10 deficiency in EGFR-mutant LA tumors decreased the apoptotic response to EGFR inhibitor therapy, leading to tumor progression during EGFR TKI treatment and worse clinical outcomes." (PMID 35579943, 2022). "Of note, Erα and GPER mediate tumor-promoting responses to estrogens by engaging in functional interactions with GF tyrosine kinase receptors including EGFR, IGF-IR, and Fibroblast GF Receptor (FGFR)." (PMID 35158804, 2022). "Overexpression of mutant EGFR in BEAS‐2B (a non‐tumour human lung epithelial cell line) also induced BMI1 expression." (PMID 35794816, 2022).
tumor (continued). "Radiation therapy is often combined with chemotherapy or targeted therapy during tumor therapy, and the duration, dose, and area of radiation have a significant impact on the severity of skin toxicity induced by EGFR inhibitors." (PMID 35223483, 2022). "Tumor samples from patients with ALK-rearranged (N = 39) and EGFR- (N = 40)/KRAS- (N = 30) mutated NSCLC were collected." (PMID 36159860, 2022). "Initial uptake studies using intratracheally administered CFSE-labelled EVs in tumor bearing mice revealed that EGFR-targeted EVs showed significantly higher levels of uptake by tumor cells as compared to untargeted EVs." (PMID 35547755, 2022). "Under-expressed OGN and EFS, compared to the normal samples, improved survival, reduced tumor recurrence, and reversed the epithelial to mesenchymal transition by inhibiting EGFR/AKT/Zeb-1 in tumors." (PMID 35741697, 2022). "Previously, EGFR and its downstream signaling pathways were reported to regulate autophagy to influence tumor progression." (PMID 35614042, 2022). "Genes in the Hedgehog, Notch, TGFβ, WNT signalling and EGFR signalling that are related to tumour proliferation, metastasis and progression were selected to further determine the presence of a significant interaction between the cell subsets." (PMID 35734169, 2022). "AKT, Raf/ERK, and STAT3 are downstream signaling factors of EGFR-mediated signaling and known to activate tumor growth and metastasis." (PMID 35572726, 2022). "Among the four HER family members, only EGFR can induce tumor proliferation through homodimerization, whereas the homodimerization of HER2, HER3 or HER4 possess no oncogenic property." (PMID 35295841, 2022). "Many of the urothelial cancer cell lines sub-typed as basal show sensitivity to EGFR targeted therapy with inhibition of tumor growth in animal models." (PMID 36293167, 2022). "Next, we concentrated on the potential involvement of genes of the EGFR-mediated EMT signature in functional aspects of tumor progression." (PMID 36076232, 2022). "Our bioinformatic analysis showed that tumor angiogenesis-related proteins, including EGFR, FGF1, FGF2, VEGRR2, and PDGFRA, were in the top 15 key targets in the PPI network of QDSJ decoction treating NF2-associated VS." (PMID 36059985, 2022). "ROS-1 rearrangement appeared in one tumor as a resistance mechanism under EGFR-TKI and crizotinib was able to obtain a partial response." (PMID 35200557, 2022). "In this pre-clinical study, we demonstrate that the brain is particularly hospitable for residual tumor cells, despite robust penetration of osimertinib and EGFR inhibition over periods of continuous treatment." (PMID 36509758, 2022). "Immunohistochemistry analysis of mouse subcutaneous tumor showed decreased expression of nuclear EGFR targets (cyclin D1, Aurora A, B-myb, c-Myc) in the absence of NONO, indicating that NONO was closely related to the nuclear EGFR transcription network." (PMID 35013116, 2022). "Plasma EGFR genotyping using circulating tumor DNA (ctDNA) is an emerging technology that has shown promise due to its accessibility, minimal invasiveness and potential clinical utility." (PMID 36292049, 2022). "We demonstrated that the overexpression of USP6NL was strongly correlated with EGFR in the GBM tumor tissue and cell lines." (PMID 35884836, 2022). "It has been shown to regulate tumor cell growth and metastasis via a variety of downstream target genes, including Selenbp1, EGFR, Foxa2, CDX2, and DDB1." (PMID 36614938, 2022). "TQ is associated with many pathways and stimulated apoptosis in tumor cells via inhibiting the STAT3 pathway by inhibiting JAK2- and Src-induced phosphorylation of EGFR-TK." (PMID 35402265, 2022).
tumor (continued). "Altogether these results suggest that the expression of CD3+ tumor-infiltrating T cells can enhance the prognostic value of EGFR expression and warrants further investigation as prognostic biomarkers for OSCC." (PMID 35957892, 2022). "USP9X has been reported to simultaneously regulate endocytosis of the EGFR by deubiquitinating its endocytic adaptor Eps15 and ubiquitin ligase Itch in tumor cell lines." (PMID 35389885, 2022). "The α-Cot-NK92 cells with ZEGFR/α-HER2-Cot recognized and lysed tumor cells depending on EGFR/HER2 surface expression levels in various tissue-derived cancer cell lines including AU565, SK-OV-3, A431, and A549 cells." (PMID 36713381, 2022). "JHU083 increases infiltration of anti‐tumor CD8+ T cells and Th1 T cells and decreases immune suppressive myeloid‐derived suppressor cells, regulatory T cells, and CD4+ Th17 cells in EGFR‐mutated lung tumors." (PMID 35861366, 2022). "The afterglow signal in the tumor region was significantly higher than that in other organs, showing that the tumor region exhibited the most active EGFR-related signaling pathway." (PMID 35105871, 2022). "Nevertheless, the proportion of EGFR+/ALK+ patients with at least 25% of tumor cells expressing PD-L1 who achieved an objective response was not substantially lower than that in EGFR−/ALK− patients (12.2% vs 16.4%)." (PMID 35958559, 2022). "The K- and N-RAS mutations, in this respect, are the most important mediators of secondary resistance to EGFR blockade, and they can be detected by circulating cell-free tumor DNA analysis." (PMID 35530345, 2022). "AFM24 is a tetravalent bispecific innate cell engager that binds simultaneously to CD16A on NK cells and macrophages and EGFR that is expressed on the tumor cell surface." (PMID 36185288, 2022). "An EGFR‐overexpressing tumor xenograft model in mice was used to study the in vivo targeting capacities of the liposomes." (PMID 34165909, 2022). "Recently, emerging findings have revealed that protein palmitoylation is crucial for many tumor-related signaling pathways, such as EGFR, RAS, PD-1/PD-L1 signaling, affecting the occurrence, progression and therapeutic response of tumors." (PMID 35637973, 2022). "Inhibition of crizotinib resistant tumor growth using EGFR-MET bispecific antibody affirmed our theory on EGFR overexpression as a bypass signaling pathway in this patient case." (PMID 36338758, 2022). "After propensity score matching, 53 EGFR-TKI treated patients and 53 EGFR-TKI treated patients with tumor resection were analyzed." (PMID 36581631, 2022). "Our results show that increased CXCL10 levels during early EGFR-TKI treatment stimulate oncogenic signaling of persistent tumor cells to contribute to EGFR-TKI resistance via autocrine and paracrine pathways." (PMID 36612121, 2022). "Detection of EGFR amplification by FISH has been described in up to 16% of PT and has been associated with tumor progression." (PMID 35158935, 2022). "The rare frequency of those mutations, such as KRAS, NRAS, BRAF, EGFR, and HER2, are also rarely found in other HPV-related malignancies, as well as the usual low tumor mutation burden (TMB), with a mean number of 2.5–3.5 somatic mutations/Mb." (PMID 36009576, 2022). "Another important receptor involved in the proliferation and survival of tumor cells is the epidermal growth factor receptor (EGFR)." (PMID 36077739, 2022). "Both when EGFR-expression was evaluated using HGU133 microarrays and when using RNA-sequencing, 17 of the 19 models demonstrated a robust correlation between EGFR-expression level and relative Erlotinib-induced tumor regression." (PMID 35139880, 2022). "Comparison of the three EGFR-TKIs was based on whole-body distribution and their target uptake by predicting the tumor-to-lung ratios." (PMID 36451855, 2022).